LINC00519 (long independently transcribed non-coding RNA 519)
Synonyms: formerly C14orf30
Gene: Long non-coding RNA gene on chromosome 14 (51,304,101 to 51,331,955, reverse strand). Ensembl gene ENSG00000258955.
Diseases named in the same sentence as LINC00519 in open-access papers:
LINC00519 is named in the same sentence as 8 diseases in open-access papers, as found by Europe PMC text mining. Sharing a sentence is not in itself a finding about the gene and the disease. The quoted sentences say what the papers report.
lung squamous cell carcinoma (3 papers, 2020 to 2025). "The higher levels of LINC00519 in lung squamous cell carcinoma are associated with a worse outlook for patients, and research has also shown that LINC00519 may speed up the progression of the disease by interacting with miR-450b-5p and miR-515-5p, and by regulating a protein called YAP1." (PMID 40299524, 2025). "LINC00519 was overexpressed and related to a poor prognosis in lung squamous cell carcinoma (LUSC) patients, which promoted tumor progression via miR-450b-5p/miR-515-5p/YAP1 pathway." (PMID 35873495, 2022).
glioma (2 papers, 2022). A benign or malignant brain and spinal cord tumor that arises from glial cells (astrocytes, oligodendrocytes, ependymal cells). "The silence of LINC00519 restrained the migration and invasion of glioma cells." (PMID 35847925, 2022).
lung adenocarcinoma (2 papers, 2020 to 2022). A carcinoma that arises from the lung and is characterized by the presence of malignant glandular epithelial cells. "Additionally, we discovered that LINC00519 also showed 3‐5‐fold upregulation in lung adenocarcinoma (LUAD, another subtype of NSCLC) cells (A549 and H1299) versus normal HBE cells, which was similar to LINC00519 upregulation in LUSC cells." (PMID 32297697, 2020). "Additionally, we also confirmed that CBP/P300 had same impact on lung adenocarcinoma (LUAD) cells, indicating that LINC00519 upregulation was universally attributed to CBP/P300 in NSCLC." (PMID 32297697, 2020).
pancreatic cancer (1 paper, 2024). "We found that LINC00519 and LINC02004 were highly expressed in pancreatic cancer cell lines, while PAN3-AS1 was lowly expressed." (PMID 39872533, 2024).
LINC00519 also shares sentences with these, for which no sentence is quoted: cancer (1 paper); sarcoma (1); thyroid papillary carcinoma (1); tumor (1).